MTOR (mechanistic target of rapamycin kinase)
Diseases named in the same sentence as MTOR in open-access papers (continued):
Sharing a sentence is not in itself a finding about the gene and the disease.
infection (continued). "Our live–dead staining with FVD660 additionally verified that the increased mVenus response is not due to cell debris or treatment/infection-induced cell death but rather from mTOR activation." (PMID 38912807, 2024). "In conclusion, the novel compound MAE derived from marine fungus inhibits the infection of IAV both in vitro and in vivo and may block IAV replication through targeting the cellular Akt-mTOR-S6K pathway." (PMID 38786581, 2024). "However, mTOR inhibition had distinct outcomes in terms of the number of antigen-specific CD8+ T cells between these early and late time points of infection." (PMID 36378537, 2023). "mTOR expression in the AKT2 inhibitor group and the mitochondrial autophagy inhibitor group was 0.761 ± 0.213 and 0.803 ± 0.286, respectively, and showed significant differences compared with the infection model group (P < 0.05)." (PMID 37077346, 2023). "Finally, infection with DENV and YFV-17D activated mTOR signaling to a similar extent—about 0.5-fold over background levels (mock-infected cells)." (PMID 37227282, 2023). "To further investigate the mTOR and autophagy status during TGEV infection, we infected PK-15 cells with TGEV and monitored the phosphorylation of mTOR and its downstream factor ULK1 at 8 and 12 hours post-infection." (PMID 37377422, 2023). "Furthermore, we showed that DTMUV infection activated the ERK and AMPK pathways, resulting in decreased phosphorylation of the autophagy repressor mTOR, subsequently leading to autophagic induction." (PMID 37936178, 2023). "Compared with the infection model group, the mitochondrial autophagy inhibitor group exhibited significantly decreased levels of p-AKT2 and p-mTOR, whereas the levels of these proteins were significantly increased in the mitochondrial autophagy inducer group (P < 0.05)." (PMID 37077346, 2023). "The importance of both MTOR and TRPML1-TFEB pathways in clearing intracellular bacteria is underscored by the numerous ways in which pathogens manipulate these pathways to establish a successful infection." (PMID 40395298, 2023). "Compared with the infection model group, the mitochondrial autophagy inhibitor group exhibited significantly lower levels of p-AKT2 and p-mTOR, whereas the mitochondrial autophagy inducer group exhibited significantly higher levels of these proteins (P < 0.05)." (PMID 37077346, 2023). "A 52% discontinuation rate (19% due to infections) of mTOR inhibitors in combination or without calcineurin inhibitors was published in 147 patients in a single center retrospective analysis without reporting details in the CNI-free subgroup." (PMID 37200246, 2023). "Next, in order to examine the role of mTOR in antigen-specific CD8+ T cells after fully establishing T cell exhaustion, rapamycin was administered to LCMV chronically infected mice for 30 days from 1 month to 2 months after infection." (PMID 36378537, 2023). "Inhibition of mTOR signaling in DENV-infected HepG2 cells, BHK-21 cells and mouse neuroblasts, human umbilical vein endothelial cells (HUVECs), and megakaryocytes accelerated the infection." (PMID 37227282, 2023). "mTOR inhibitors were less frequently used among patients with UTI compared to those who did not have the infection (22.6% vs 47.1%, p < 0.001)." (PMID 37791170, 2023). "In the current manuscript, DENV C protein fails to exhibit a significant decrease during infection without autophagy activation, such as starvation or mTOR inhibitor." (PMID 35865923, 2022). "In this study, we explore the consequences of a physical protein-protein interaction between dengue non-structural protein 5 (NS5) and host cell mTOR proteins during infection." (PMID 36171757, 2022).
infection (continued). "Ingenuity Pathway Analysis of scRNA-Seq data indicated the antigen presentation pathway was increased with infection, while EIF2 signaling is the top downregulated pathway followed by eIF4/p70S6k and mTOR signaling in multiple cell types including macrophages, blood and lymphatic endothelial cells." (PMID 35789215, 2022). "However, addition of FBS with a concentration ≥10% rescued transcriptional expression of mTOR and IGF1 and 30% FBS addition significantly increased expression of mTOR and IGF1 compared to the infection group and normal group." (PMID 36423079, 2022). "Autophagy-deficient cell model used in viral infection showed that IAV regulated autophagy to increase viral genomic RNAs by decreasing the phosphorylation of mTOR, 4E-BP1 and S6 at the infection early stage and promoting the phosphorylation of p70S6K at the infection late." (PMID 34967267, 2022). "Our study shows that the infection pathogens could significantly increase the expression of AMPK and decreased mTOR as compared to NC group." (PMID 33574492, 2021). "Rapamycin blocked the infection-induced upregulation of BCL-2 and BCL-Xl, suggesting that modulation of mTOR signaling may be engaged in this reaction." (PMID 33924101, 2021). "After NAC injection, mTOR was up-regulated and AMPK down-regulated compared with infection group." (PMID 33574492, 2021). "Finally, we also found that the expression of mTOR mRNA level decreased significantly, and increased AMPK mRNA level in the pathogen infection group." (PMID 33574492, 2021). "In this study, we show that Ag-experienced (Ag-exp) CD4+ T cell exhaustion during Plasmodium yoelii nonlethal infection occurs alongside the reduction in mammalian target of rapamycin (mTOR) activity and restriction in CD4+ T cell glycolytic capacity." (PMID 32817333, 2020). "In addition, mTOR-HIF-α pathway activation promotes aerobic glycolysis and inflammation, inducing granuloma formation and the host innate defense early during infection." (PMID 33262773, 2020). "Western blotting of whole protein, MP, and cytosolic fractions of DCs showed increased membrane localization of mTOR in infected cells, even though the total protein content did not significantly vary between WT (no infection) and infected DCs." (PMID 32041786, 2020). "In particular, FL13 infection presented a reduction in the oxidative mitochondrial metabolism (both oxidative phosphorylation and citric acid cycle), whereas Lena mostly modulated the aerobic glycolysis (AKT/mTOR/PI3K) pathways." (PMID 33365028, 2020). "However, we found a significant inhibition of HIF-1α through 24hpi and 48hpi of the infection, suggesting a crosstalk between the SARS-CoV-2 and the Akt/mTOR/HIF-1 signaling pathways." (PMID 32691695, 2020). "The p-mTOR was nearly absent at 1 and 2 h post-infection with ctpFCKD, as opposed to H37Rv or the vector control." (PMID 33042857, 2020). "It has been published that infection of lung epithelial cells with Sendai virus, which is primarily recognized by RIG-I but can also be detected by MDA5 and TLR7, induces the phosphorylation of several mTOR kinase substrates suggesting increased mTOR activity." (PMID 33013932, 2020). "The contribution of mTOR inhibitors administered with conventional chemotherapy drugs may therefore be different in the treatment of primary, HBV- and HCV-related infection, and of secondary liver tumors." (PMID 33362215, 2020). "In Huh7 hepatoma cells, infection with HCV leads to induction of the UPR and subsequently to an inhibition of the phosphatidylinositol 3-kinase (PI3K)/AKT/mammalian Target of the Rapamycin (mTOR) signaling pathway, resulting in induction of autophagy." (PMID 32283772, 2020).
infection (continued). "At last, we compared the difference of T-bet expression between Lck-mTOR mice and Lck-TSC1 mice under the same infection degree (MSS group) and found that in the same MSS group, Lck-mTOR mice had more T-bet expression than WT mice, while Lck-TSC1 mice had less expression than WT mice." (PMID 32431684, 2020). "The steady-state levels of S6, a downstream target of mTOR, were not altered in the uninfected Taco1mut/mut and Taco1wt/wt mice, whereas infection reduced the phosphorylated levels of S6 in the hearts of both control and mutant mice." (PMID 32130224, 2020). "In support of the link between fungal melanin and mTOR/HIF-1α signaling, infection of macrophages with melanin-coated live ΔrodA/pksP conidia restored both p-p70S6K and HIF-1α translocation to the nucleus to levels comparable with those obtained after infection with the Δku80 strain." (PMID 32385235, 2020). "In contrast, rapamycin, another mTOR inhibitor, enhances HIV-1 vector infection." (PMID 31450557, 2019). "Next, we analyzed the kinetics of mTOR activity in TFH cells at day 2, 5, and 8 post infection." (PMID 29875775, 2018). "Inhibition of mTOR by rapamycin displayed only minor effects on SCV infected macrophages after 0 and 2 h post internalisation, but the level of the enzyme significantly increased after 24 h post infection with the SCV strain (p<0.05)." (PMID 30412620, 2018). "Initially, it was speculated that by targeting the mTOR complex during the lytic phase of CMV infection, sirolimus abrogates the infection, and inhibits reactivation since CMV utilizes the mTORC1 pathway for viral replication." (PMID 30619313, 2018). "We hence conclude that the activation of mTOR seen during WT SFV infection as a downstream effect of infection-induced PI3K/AKT hyperactivation is not critical for virus growth in vitro." (PMID 29377936, 2018). "Finally, a link between mTOR-dependent ASCT2 expression and infection by Salmonella enterica has been described." (PMID 30234109, 2018). "Furthermore, stable infection with lenti-UCA1-siRNA inhibited the expression of AKT3, p-AKT3, p-mTOR, and S6K, and increased the expression of EIF4E in BGC-823 cells, when compared with blank and negative control cells." (PMID 29212166, 2017). "In addition, we showed that high expression of CTLA-4 and low levels of IL-2 prevented mTOR activation and Otub-1 protein expression, and maintained GRAIL expression, which inhibited T cell proliferation during the acute phase of the infection." (PMID 28114324, 2017). "On examining mTOR activity, we did not observe phosphorylation of 4EBP1 during the acute phase of infection although it was detected later on, thereby allowing Otub-1 expression and GRAIL degradation." (PMID 28114324, 2017). "Sindbis virus (SINV) is another alphavirus that was found to suppress phosphorylation of Akt, mTOR, 4EBP1 and S6K1 in HEK cells at late times post-infection, suggesting that SINV replication blocks the mTOR pathway to modulate cell survival and protein synthesis." (PMID 27231932, 2016). "To confirm whether mTOR is repressed by BTV1 in a replication stage-dependent manner, we performed an immunoblotting assay using samples collected at various infection times." (PMID 26976147, 2016). "In contrast, the increased levels of mTOR phosphorylation were not parallel with the infection of CSFV C in SUVEC." (PMID 27330868, 2016). "Under these infection conditions, MTOR inhibition was initiated after the infections were synchronized and therefore did not interfere with bacterial uptake." (PMID 27942021, 2016). "Finally, mTOR inhibitors regulate the differentiation of memory CD8 T-cells, improving the immune reaction against BKV after infection." (PMID 27047803, 2016). "In the absence of TGF-β, blocking mTOR with rapamycin during the first week of infection was sufficient to restore Tfh cell differentiation and suppress T-bet and GrzB expression." (PMID 25569154, 2015).
infection (continued). "Previous studies showed that infection with WT L. pneumophila (but not the ΔdotA strain), resulted in ubiquitination of positive regulators of mTOR kinase and led to diminished mTOR activity." (PMID 26219498, 2015). "Overall, this result indicated that proteolytic degradation of MTOR was not the crucial trigger for autophagy induction in BMDM after infection with L. m.." (PMID 26226952, 2015). "Simian virus 40 (SV40) infection also stimulates both AMPK and mTOR activity." (PMID 24098109, 2013). "For example, infection with human cytomegalovirus (HCMV) increases both AMPK and mTOR activity." (PMID 24098109, 2013). "Bayesian network modeling identified effects of infection on several interrelated signaling pathways including MAPK, Phosphatidylinositol, mTOR, Calcium, Toll-like Receptor, CCR3, Wnt, TGF-β, and Regulation of Actin Cytoskeleton and Apoptosis that were used to model of host-pathogen interactions." (PMID 22096503, 2011). "While it has previously been shown that the Ras-PI3K-Akt-mTOR signaling pathway is involved in WSSV-induced host metabolic reprogramming, here we further investigated whether this same pathway also modulated de novo nucleotide synthesis during WSSV infection." (PMID 40264189, 2025). "Pattern recognition receptors (PRR), mammalian target of rapamycin (mTOR), AMP-activated protein kinase (AMPK), the hexosamine biosynthesis pathway (HBP), and O-GlcNAcylation are not only responsive to nutrient fluxes and metabolic stress but also to infection and danger signals." (PMID 41227388, 2025). "Therefore, we examined the activation of the AMPK and mTOR pathways in AEC-II cells after H37Rv infection and found no significant changes in their activation." (PMID 38397085, 2024). "Interestingly, despite the number of study patients being lower than expected due to high infection rates during enrollment, we found an overall increase in SARS-CoV-2-specific immune responses in patients switched to CNI/mTOR-i as compared to those who remained on CNI/MMF." (PMID 39439787, 2024). "mTOR inhibitor, PP242, treatment directly inhibits CK1α kinase activity and disrupts the LT interaction with both β-TrCP and Skp2, which explains a greater inhibition effect on LT destruction complex, resulting in enhanced MCPyV replication and infection shown in the previous studies." (PMID 38940554, 2024). "Expression of mTOR did not decrease until 48 hours post infection." (PMID 37026095, 2023). "Post HIRRV infection under 10 °C and 20 °C, the enriched immune-related DEPs were both involved in RLR and NLR signaling pathways, apoptosis, phagosome and lysosome, and the DEPPs were also both enriched in spliceosome, mTOR signaling pathway and RNA transport." (PMID 37627029, 2023). "The co-expression network analysis from the human post-mortem study indicated that signalling pathways interrelated with the mTOR pathway may be up-regulated in the endothelial cells of the PFC in BPD and that pathways related to infection are also enriched in the module." (PMID 35508467, 2022). "Furthermore, L-arginine did not provide further mTORC1 activation beyond that induced following infection, suggesting that L-arginine was not directly working through mTOR to regulate glycolysis in Mtb-infected macrophages." (PMID 34054815, 2021). "australis infection differentially regulated a significant number of genes in bone marrow-derived macrophages (BMMs) in an Atg5-depdent fashion as determined by RNA sequencing and Ingenuity Pathway Analysis, including genes in the molecular networks of IL-1 family cytokines and PI3K-Akt-mTOR." (PMID 33912163, 2021). "Paradoxically, the virus also induces downregulation of mTOR, indicating that the SARS-CoV-2-induced autophagy block might be in part independent of mTOR activity, at least during the early phases of infection." (PMID 33182802, 2020).
infection (continued). "The initial absence of mTOR activity could mean that Salmonella targets mTOR for invasion or this is just a cellular response to prioritize cellular activities during infection." (PMID 32674261, 2020). "Moreover, the authors demonstrated that SINV replication does not require the PI3K/Akt/mTOR pathway, and that later during infection, SINV suppresses Akt/mTOR activation in HEK cells." (PMID 31681621, 2019). "Interestingly, the SsD treatment of cells markedly inhibited VP1 levels induced by EV-A71 infection in the presence or absence of Torin-1, another mTOR inhibitor." (PMID 30820356, 2019). "As livers were collected 48 h post infection, we hypothesize that significantly increased mTOR phosphorylation may be part of the negative feedback regulating process in chickens to the increased autophagy induced by S. Enteritidis infections." (PMID 32009981, 2019). "The elevated expression of ELOVL7 transcript and protein following infection was found to partially depend on the expression of the viral protein UL38, which has previously been demonstrated to manipulate cellular metabolism by indirectly increasing mTOR activity." (PMID 30699959, 2019). "Besides this paradigmatic antagonism of AMPK and mTOR-related pathways, Akt and forkhead box O (FOXO) have been recently found to mediate infection-induced cachexia, as indicated by Drosophila FOXO mutants surviving infection longer than wt conspecifics." (PMID 29997622, 2018). "Thus, activation of mTOR complex in SFV- and RRV-infected cells, might contribute to the high and sustained levels of viral protein synthesis late into infection." (PMID 29495654, 2018). "However, to our knowledge, rapamycin, its analogs and dual mTOR/PI3K inhibitors have not been used in in vivo models of infection with Leishmania spp." (PMID 30133440, 2018). "Interestingly, the infection of Mtb H37Rv did not alter the phosphorylation of mTOR, rather than reduce the expression of total mTOR protein in U937-derived macrophage-like cells." (PMID 30356420, 2018). "Autophagy is induced by several cues including nutrient and growth factors availability, energetic status, hypoxia, oxidative stress and pathogen infection; these stress signals are integrated by mTOR that, under nutrient rich conditions, acts as a negative upstream regulator." (PMID 29692710, 2018). "Next, the impact of sustained MTOR activation on Legionella intracellular life cycle was determined in macrophage infections under serum-free conditions that were allowed to progress for less than a single infection cycle (~16hrs) in the presence or absence of MTOR inhibitors." (PMID 27942021, 2016). "Genetically deficient BMDMs in CCR5 (CCR5-/-) or treatment with specific inhibitors to JAK2 (Tyrphostin AG490), NF-κB (CAPE), AP-1 (Tanshinone) or mTOR (Rapamycin) did not yield significant differences in cytokine production after infection, if compared to WT or untreated controls." (PMID 27679624, 2016). "Early during infection, TGF-β signaling suppressed the expression of the high affinity IL-2 receptor α chain (CD25) on virus-specific CD4 T cells, which tempered IL-2 signaling and STAT5 and mammalian target of rapamycin (mTOR) activation in Tfh precursor CD4 T cells." (PMID 25569154, 2015). "While extremely effective at inducing pathogen killing, inhibiting mTOR activity may not faithfully recapitulate the biochemistry induced during infection." (PMID 24528777, 2014). "However, there is no information on whether autophagy is activated during FeHV-1 infection nor on how this infection modifies PI3K/Akt/mTOR pathway." (PMID 37026095, 2023). "However, we did not detect the fungal burden or other infection markers, which could help us to understand the role of mTOR mediated CD8+ T cell autophagy improvement in pathogen clearance and the final prognosis in lethal fungal sepsis." (PMID 34220329, 2021).